GNLY (granulysin)
Diseases named in the same sentence as GNLY in open-access papers (continued):
Sharing a sentence is not in itself a finding about the gene and the disease.
tumor (continued). "Multiple publications have confirmed the anti-tumor activity of GNLY." (PMID 33842346, 2021). "We are currently investigating the potential role of granulysin in NK EV-mediated tumor death." (PMID 34368150, 2021). "NK3.3-derived EVs also contained cytotoxic proteins required for NK anti-tumor activity: NKLAM, perforin, granzymes A and B, and granulysin, as well as immune-associated proteins MHC I and II and DNAX Accessory Molecule (DNAM-1; CD226), an activating receptor on NK cells." (PMID 34368150, 2021). "Interestingly, the antitumor activity of granulysin was associated with a massive NK cell infiltration, suggesting a possible immunogenic effect of granulysin-induced tumor cell death." (PMID 34829955, 2021). "This could be because NK cells secrete perforin and granzymes, and granulysin through the granule exocytosis pathway, which leads to the destruction of tumor cells or virus-infected cells." (PMID 34444188, 2021). "A set of mechanisms acquired by tumor cells that negatively target granulysin expression, hence attenuating the antitumor potential of NK cells, might explain these observations." (PMID 32466293, 2020). "Our data suggest that Vδ2+γδ T cells, through the production and release of granulysin, may be involved in orchestrating adaptive immunity against tumour." (PMID 32794189, 2020). "Granulysin is a protein contained in the granules of cytotoxic T lymphocytes (CTLs) and human natural killer (NK) cells that possesses cytolytic potential on microbes and also on tumor cells." (PMID 32859066, 2020). "A cytolytic 9000 MW isoform of granulysin kills tumour cells directly, whereas a 15 000 MW precursor has been hypothesized to cause both the maturation and migration of dendritic cell (DC) populations." (PMID 32794189, 2020). "This is of interest as it suggests that in a physiological setting, granulysin released by Vδ2+γδ T cells in response to a tumour target may contribute to the influx of immature DC to the tumour site." (PMID 32794189, 2020). "The remit of this study was to determine whether Vδ2+γδ T cells released granulysin in response to a tumour target, and to investigate the functional consequences of this response." (PMID 32794189, 2020). "Release of granulysin by γδ T cells contributes to tumour cell killing." (PMID 32794189, 2020). "However, considering a possible general clinical application of this treatment, it would be desirable to perform systemic injections of the treatment and, if possible, target granulysin specifically towards the tumor." (PMID 32859066, 2020). "Despite this, our data suggest that granulysin may be released by Vδ2+γδ T cells that infiltrate and recognize tumours in vivo, which are sensitive to killing by this cell type." (PMID 32794189, 2020). "The presence of intracellular granulysin within this subpopulation before recognition of tumour and subsequent activation may allow a more rapid release of granulysin into the surrounding environment when activation of the cell does occur." (PMID 32794189, 2020). "The significantly higher baseline expression of granzyme and granulysin in the tumor microenvironment of patients who subsequently experience pCR are consistent with the preclinical models that indicate synergy between cytotoxic T cell activity and the antitumor effect of chemotherapy." (PMID 30967156, 2019). "We examined the GNLY expression and its effects on tumor growth using this system." (PMID 29137359, 2017). "Importantly, we found that the serum level of GNLY correlated negatively to the tumor volume in both CL1-5 and HT29-bearing HIS mice (p<0.01)." (PMID 29137359, 2017). "Experimentally, GNLY promoted survival in transgenic mice with tumor." (PMID 29137359, 2017). "In addition, GNLY obtained from HIS mice serum suppressed the viability of tumor cells and induced apoptosis." (PMID 29137359, 2017). "Previous studies suggested the anti-tumor function of GNLY in cancer patients." (PMID 29137359, 2017).
tumor (continued). "Importantly, GNLY down-regulated the tumor growth via apoptotic pathways and the serum level of GNLY was correlated with the inhibition of tumorigenesis in HIS mice." (PMID 29137359, 2017). "In addition, CC-3 induced secretion of antitumor cytokines (IFN-γ, TNF, IL-2) and effector molecules (granzymes, perforin, and granulysin), which are known to promote tumor cell death, and also induced potent and long-lasting tumor cell lysis by the activated T cells." (PMID 40707958, 2025). "The significant Increase in the expression of genes such as GZMB (granzyme B) and GNLY (granulysin) in CD8+ T cells of patients unresponsive to anti-PD1 treatment could reflect an attempt by the immune system to fight the tumor through the activation of CD8+ T cells." (PMID 40182035, 2025). "Notably, the transfer of CART19-28z SNX9 KO was accompanied with increased serum levels of anti-tumor effector molecules IFNγ, Perforin, and Granulysin, while we detected a decrease in IL10 and IL6 (human CCL5 could not be detected in the serum)." (PMID 36732507, 2023). "New clonotypes appearing in blood or tumor at disease progression were enriched for genes associated with cytotoxicity or stemness (FGFBP2, GNLY, GZMH, GZMK, IL7R, SELL and KLF2), and these might be harnessed for alternative cellular therapy or cytokine therapy." (PMID 36514045, 2022). "Vδ2+γδ T cells are capable of the release of two isoforms of granulysin; a cytolytic 9000 MW isoform, which kills tumour cells directly, and a 15 000 MW precursor, which has been hypothesized to cause both the maturation and migration of dendritic cell (DC) populations." (PMID 32794189, 2020). "Their study systematically evaluated the efficacy of this granulysin-based immunotoxin, MFE23GRNLY, in HeLa-CEA tumor-bearing mice, providing the first proof-of-concept for its use in cancer therapy." (PMID 40691738, 2025). "One subpopulation expressed CD44 + CXCR3 + CXCR4 + PRF1 + and GZM family genes, while the other expressed XCL1 + NCAM1 + GNLY + and KIR family genes, suggesting that these T cells possess a robust capacity to mediate tumor cell apoptosis." (PMID 40411616, 2025). "In contrary we found upregulated (EOMES, TNFSFR9, TIGIT, KLRD1) and downregulated genes (PAG1, GNLY, ANXA1, FGFBP2) that are involved in tumor escape from immune surveillance by suppressing T-cells or by reprogramming T-cells toward T-cell exhaustion." (PMID 40079005, 2025). "Upregulated EOMES and TNFSFR9 and downregulated genes (PAG1, GNLY, ANXA1, FGFBP2) that are involved in tumor escape from immune surveillance by suppressing T-cells or by reprogramming T-cells toward T-cell exhaustion." (PMID 40079005, 2025). "Consistent with previous findings, we observed that Tcr-1-positive CD8+ subclone was identified as high expression of GNLY, ZNF683, CXCL13, and were furtherly proven of high avidity against SYT-SSX fusion-positive tumor cells." (PMID 39748060, 2025). "High TIL and its subset (CD4+, CD8+, CD56+, CD57+, GNLY+, and GZMB+ TIL) infiltration correlated with favorable clinicopathological features of tumor." (PMID 39643914, 2024). "ITGAE is associated with a group of genes that have a cytotoxic function in CD8 cytotoxic T cells (CTSW, GNLY, NKG7, PRF1, GZMB, KLRK1) up-regulated in the tumor, identifying resident CD8 T cells in the tumor to have a highly cytotoxic and activated phenotype." (PMID 39548591, 2024). "Consistently, the tumor-infiltrating GZMAhigh NK subcluster expressing a high level of cytotoxic genes (GZMA, GZMB, GZMK, GZMM, GZMH, PRF1, and GNLY) and FASL and TRAIL genes was most enriched in the PD-1+SMI group." (PMID 37430270, 2023). "We also found that several key cytotoxic genes (such as NKG7, GNLY, PRF1) were more highly expressed in the non-tumor regions." (PMID 38123589, 2023). "Accordingly, FGFBP2+NKT cells expressed the highest levels of cytotoxic genes, such as GZMB, GZMH, PRF1, and GNLY, indicating that FGFBP2+NKT cells had the strongest tumor-killing effects." (PMID 38065972, 2023).
tumor (continued). "We found that 47 genes were upregulated in tumor tissues compared to normal tissues, such as CD48, TIGIT, GNLY, CCL19, CCL5, CXCL13, CCL17 and NKG7." (PMID 36713530, 2022). "Comparison of genes differentially expressed between the subcluster C9 of exhausted CD8+ cells from tumors and normal tissues showed GNLY and ITM2A were highly expressed in normal tissues, and high expression of FABP5 and RPS6 was exhibited in tumor tissues." (PMID 35874785, 2022). "Cytotoxicity-related genes GNLY, NKG7, GZMB and GZMA were downregulated in both tumor-derived CD4+ and CD8+ T cells." (PMID 36506053, 2022). "CD8-05-FGFBP2 cluster exhibited a CD8+ effector phenotype, upregulating genes involved in cytotoxicity and anti-tumor activity: FGFBP2, GNLY, FCGR3A, GZMH, PRF1, TGFBR3, and GZMB." (PMID 36350695, 2022). "While enhanced secretion of granulysin and granzyme B directly account for increased tumor lysis, IFN-γ and TNF-α stimulate the endogenous immune system and indirectly enhance anti-tumor activity." (PMID 33807875, 2021). "Interestingly, it has been observed that granulysin triggers cancer cell apoptosis through caspase-dependent and independent mechanisms in hematological B-cell neoplasms, and therefore it plays a central role in immune-related mechanisms of tumor development and progression." (PMID 33809641, 2021). "Granulysin (GNLY), a novel cytolytic protein lytic against a variety of tumor cells and microbes, is also with a higher expression in dNK cells." (PMID 34054831, 2021). "Through the release of granulysin, this cell population may contribute to the arrival of immature DC populations to a site of tumour, and may then further contribute to the migration of matured DC away from the tumour site, and towards lymph nodes to activate the adaptive immune response." (PMID 32794189, 2020). "To further assess the contribution of granulysin released by Vδ2+γδ T cells in response to tumour in the maturation and migration of DC, it would be important to next determine whether we could replicate our findings using supernatants taken from the co‐culture of these cells with tumour targets." (PMID 32794189, 2020). "A high immune infiltrate within the tumor and at the tumor invasive margin, especially when being composed of Th1 cells expressing IFN-γ, as well as CTLs producing granzymes and granulysin, is a common characteristic of tumors having a favorable prognosis." (PMID 31731645, 2019). "In a study in colon cancer, the densities of CD3+, CD8+, granulysin, and granzyme B (GZMB)+, and CD45RO+ cells in each tumor region (tumor center and invasive margin) were shown to be prognostic." (PMID 29385739, 2018). "In our analysis, we found that in adult ALK-negative ALCLs, the expression of granulysin was less strong and intense than in ENKTL cases and in addition restricted to a small proportion of tumour cells (less than 25%; score 1)." (PMID 30151671, 2018). "When exposed to target tumour cells, CD8+ cytotoxic T cells (CD8+ Tc) directly release cytotoxins, including perforin, granzymes and granulysin." (PMID 28504276, 2017). "Equally important, the addition of GNLY isolated from HIS mouse serum induced apoptosis in both CL1-5 and HT29 tumor cells." (PMID 29137359, 2017). "Notably, compared with the PD‐L1− tumor group, the upregulated differentially expressed genes (DEGs) in the CD8‐C2‐Texterm subset from PD‐L1+ tumor group included exhaustion‐related genes such as HAVCR2, CXCL13, PDCD1, TIGIT, LAG3, BATF, GNLY, and CTLA4." (PMID 41194450, 2026). "The study highlighted two major challenges: the reliance on intratumoral injection and the lack of tumor specificity of recombinant granulysin." (PMID 40691738, 2025). "Cytotoxic/effector genes (GNLY, GZMA, GZMK, IFNG, NKG7, PRF1) were primarily expressed by T and NK cells, with notable upregulation in stRNA‐seq‐defined invasive front and tumor core regions." (PMID 41057994, 2025).
tumor (continued). "MAP2K2-KO in tumor cells also results in significant overexpression of the immune checkpoint receptor ligand PDCD1LG2 (LFC: 0.2, Q: 0.01) and downregulation of the marker of cytotoxicity GNLY (LFC: −0.29, Q: 0.03)." (PMID 40081369, 2025). "In addition, we observed an increase in the expression of cytotoxicity (PRF1, GNLY, GZMB) and proliferation (MKI67) markers in the CD8+ T cells in PI3K/mTORi+PD‐1i‐treated tumours." (PMID 38711203, 2024). "Conversely, immune activity-related signatures, including PRF1, GNLY, GZMA, GZMB, and interferon regulatory factor 1, play crucial roles in tumor cell recognition and tumoricidal, with connections to extended survival, and identifying responders to anti-PD-1 antibody treatment." (PMID 38956740, 2024). "Similarly, FGFBP2+ NK cells also highly expressed markers like GNLY, NKG7, and PRF1, indicating a strong anti-tumor immune response." (PMID 39093451, 2024). "Selected genes are reflecting main anti-tumor immune pathways, such as Th1 signaling (IFNG, TBX21, CD8A/B, IL12B, STAT1 and IRF1), Th1 chemoattraction (CXCL9, CXCL10 and CCL5) and cytotoxic functions (GNLY, PRF1, GZMA, GZMB and GZMH)." (PMID 37726776, 2023). "Notably, NK cells, which displayed high expression levels of GNLY, NKG7, CCL3, and KLRD1, were enriched in tumor tissues, especially in HM tissues." (PMID 37612267, 2023). "We observed that upon stimulation with tumor cells or tumor cells plus Obinutuzumab, the secretion of IFN-γ, Granzyme B, Perforin, Granulysin, and IL-10 was significantly increased in NK cells expressing hnCD16FR, whereas Granzyme A was secreted at high levels only in NK cells expressing hnCD16." (PMID 37316891, 2023). "They similarly suggested that there is not a single mediator of tumor killing but that perforin, granzyme A, granzyme B and granulysin in NK EVs together play prominent roles in inducing cytotoxicity." (PMID 37818374, 2023). "NK-92/5.28.z cells secreted high amounts of effector molecules such as granzymes, granulysin, and perforin upon interaction with RMS tumor cells, while the levels of secreted cytokines such as TNF-α, IL-2, IL-6, and IL-4 were minimal or below the detection limit." (PMID 33809981, 2021). "The increased expression of cytotoxic effector molecules GZMA, GZMB, GZMH, GZMM, GNLY, NKG7, and PRF178 but also of the thioredoxin function inhibitor TXNIP79, demonstrates a potent effector capacity to eliminate malignant cells and suppress tumor growth." (PMID 33602930, 2021). "Granulysin refers to one protein in the granules of natural killer cell and human cytotoxic T lymphocyte, exhibiting cytolysis activity against tumor and microbe, whereas there is no information concerning the mechanisms involved in RA." (PMID 34691030, 2021). "On the other hand, tumor-infiltrating lymphocytes (TILs), that are part of the antitumor immune response, also express TIA1 along with a series of cytotoxic cytokines (e.g., granzyme B and granulysin), suggesting an active antitumor immune response." (PMID 32707930, 2020). "It is interesting that the pre‐treatment of Raji cells with ZA did not increase the release of granulysin to a level comparable to that seen following culture of Vδ2+γδ T cells with Daudi cells, despite increasing the amount of tumour cell death." (PMID 32794189, 2020). "In the present work, we developed a second immunotoxin combining granulysin and the anti-Tn antigen single-chain Fv antibody fragment SM3, that could have a broader application in tumor treatment than our previous immunotoxin." (PMID 32859066, 2020). "Culture of Vδ2+γδ T cells with untreated Raji cells did not induce any secretion of granulysin above that produced by Vδ2+γδ T cells cultured alone, and also did not result in any marked increase in tumour cell death." (PMID 32794189, 2020). "In the present study, we are not able to quantify serum levels of granulysin from blood samples and to correlate with its expression in tumour tissue." (PMID 30151671, 2018).
tumor (continued). "CD8+ cytotoxic T cells and NK cells are required for anti-viral and anti-tumor responses through their lytic activity (mediated by granzymes, granulysin and perforin) and non-lytic mechanisms through release of anti-viral cytokines." (PMID 25956355, 2015). "First, to compare the profiles of tumor-infiltrating cytotoxic T lymphocytes between invasive and noninvasive EMPD, we employed immunohistochemical staining for CD8, granulysin, TIA-1, and perforin." (PMID 23606867, 2013). "Responders (CR/PR) exhibited robust cytotoxic T-cell activation characterized by up-regulation of GNLY, GZMB, and CXCL13, whereas non-responders (SD) uniquely showed persistent overexpression of HSPA1B, a stress-response gene associated with tumor progression and immune suppression." (PMID 42158872, 2026). "The LINC01871/miR‐4644 and miR‐185‐5p/GNLY axes might affect distant metastasis and prognosis (DFS) of CRC by regulating the radiosensitivity, ferroptosis, autophagy, and stemness of CRC cells and the tumor immune microenvironment." (PMID 38083905, 2023). "More specifically, we have recently published data showing that granulysin, released by Vδ2+ cells, can induce migration and maturation of immature DCs, suggesting the potential for BCG-expanded Vδ2+ cells to more effectively contribute to enhancing tumour antigen presentation by DCs." (PMID 35404420, 2022). "Antigens derived from tumor tissues can activate CD8+ T cells to produce anti-cancer responses, improving pore formation in target tumor cell membranes and subsequent target-cell killing by secreting cathepsin C, perforin, and granulysin to fusion target cell membranes." (PMID 36171887, 2022). "Cytotoxic CD4+ T cells also express GNLY, which has a documented role in anti-microbial immunity; although a proven role in anti-tumor responses has not been documented, profiling of single-cell clones with cytotoxic activity pointed to an enrichment of GNLY expression in this population." (PMID 34910940, 2021). "For this reason, we sought to confirm that isolated Vδ2+γδ T cells could release granulysin in response to tumour without additional activation." (PMID 32794189, 2020). "The tumor cells were not inhibited when the effect of GNLY was neutralized." (PMID 29137359, 2017). "Furthermore, the expression of GZMB and GNLY could indicate a state of chronic activation of CD8+ T cells, which could lead to exhaustion and dysfunction of T cells, hindering their effective role in eliminating tumor cells." (PMID 40182035, 2025). "Control CD4+ T-cells cultured the same way, but without peptides, produced low amounts of IFN-γ, granulysin and granzyme B and displayed poor cytotoxic activity against MHC-II-positive Capan-1 cells, which shows that the peptide-specific T cells were recognizing the tumor cells in a specific manner." (PMID 35655709, 2022).